DLK1 (delta like non-canonical Notch ligand 1)
Diseases named in the same sentence as DLK1 in open-access papers (continued):
Sharing a sentence is not in itself a finding about the gene and the disease.
osteosarcoma (4 papers, 2016 to 2023). A usually aggressive malignant bone-forming mesenchymal neoplasm, predominantly affecting adolescents and young adults. "Intriguingly, DLX6-AS1 can promote the stemness of osteosarcoma cells by regulating miR-129-5p/delta like non-canonical notch ligand 1 (DLK1)." (PMID 33117795, 2020).
preeclampsia (4 papers, 2021 to 2022). Preeclampsia is a hypertensive disorder of pregnancy that is characterized by new-onset hypertension with proteinuria presenting after 20 weeks of gestation, and depending on mild or severe forms may initially present with severe headache, visual disturbances, and hyperreflexia. "Herein we investigated the relationship between the DLK1-Dio3 imprinted miR cluster derived from placental and peripheral blood exosomes of pregnant women with preeclampsia and routine clinical diagnostic indicators, and also determined its potential as a noninvasive diagnostic marker." (PMID 36123601, 2022). "In a study that included 102 pregnant women, the median DLK1 serum concentration during pregnancy was significantly lower for women with preeclampsia than healthy pregnant women, even after adjustment for gestational age at blood sampling and birth weight." (PMID 35295988, 2022). "In this study, we assessed pregnant women with preeclampsia and healthy pregnant women to evaluate differences in expression levels of the DLK1-Dio3 imprinted miR cluster." (PMID 36123601, 2022). "Secretion of placental exosomes was found in pregnant women with preeclampsia; furthermore, the DLK1-Dio3 imprinted miR cluster comprised 10 miRs, the expression levels of which were significantly different from those in healthy controls." (PMID 36123601, 2022). "Interestingly, the expression level of the DLK1-Dio3 imprinted miR cluster was consistent between peripheral blood and placental exosomes of pregnant women with preeclampsia." (PMID 36123601, 2022). "Maternal serum DLK1 concentration rank was positively associated with risk of gestational hypertension (P = 0.01; adjusted for prepregnancy BMI) but not with GDM status." (PMID 33640968, 2021). "DLK1 was found to be higher in small-for-gestational-age (SGA) infants and infants born to mothers with preeclampsia in previous studies." (PMID 34540403, 2021). "However, the role of the DLK1-Dio3 imprinted miR cluster in preeclampsia occurrence and development has not been reported." (PMID 36123601, 2022).
rhabdomyosarcoma (4 papers, 2013 to 2024). A rare aggressive malignant mesenchymal neoplasm arising from skeletal muscle. "Dlk1 was detected in both rhabdomyosarcomas and RMS cell lines, thus it was of interest to analyze the tumor cells for specific Dlk1 splice variants." (PMID 23577150, 2013). "Dlk1 is paternally expressed and belongs to a group of imprinted genes associated with rhabdomyosarcomas but not with other primitive childhood tumors to date." (PMID 23577150, 2013). "It belongs to a group of imprinted genes, which have been associated recently with rhabdomyosarcomas but not other primitive childhood tumors, thus Dlk1 might be involved in skeletal muscle tumour formation." (PMID 23577150, 2013). "Therefore, considering that maturation arrest is proposed as a factor in the development of rhabdomyosarcomas (RMS) this study was designed to elucidate if skeletal muscle neoplasias express Dlk1, and further, to determine if Dlk1 in muscle influences myogenesis." (PMID 23577150, 2013). "Thus in neoplasias derived from mesenchymal tissues, rhabdomyosarcomas appear to be the only tumor consistently expressing Dlk1, and expression is independent of subtype." (PMID 23577150, 2013). "A subset (MEST, PLAGL1, PEG3, DLK1, IGF2) showed elevated expression in various embryonal cancers, especially rhabdomyosarcoma, as compared to non-embryonal cancers and normal tissues." (PMID 36437415, 2023). "Moreover, the presence of LOI at the delta-like non-canonical notch ligand 1 (DLK1) and MEG3 locus has been found to vary between two different histological subtypes of rhabdomyosarcoma (RMS)." (PMID 38812777, 2024).
schizophrenia (4 papers, 2014 to 2025). A major psychotic disorder characterized by abnormalities in the perception or expression of reality. "In genome-wide methylation arrays, MEG3 DMR methylation was associated with maternal smoking and in human adults, DLK1 dysregulation has been associated with schizophrenia." (PMID 30246009, 2018). "In addition, a microRNA signature associated with schizophrenia includes the down-regulation of 17 microRNAs expressed from the Dlk1-Dio3 domain." (PMID 29921775, 2018). "Ascorbic acid has been found to prevent loss of imprinting at the Dlk1-Dio3 domain in stem cells, and maternal immune response or cannabinoid exposure in adolescence alters the imprinting of Dlk1-Dio3 in the entorhinal cortex, a region implicated in schizophrenia." (PMID 29921775, 2018). "The miRNA clusters and genes within the Dlk1-Dio3 region are differentially regulated in various diseases such as cancer and schizophrenia as well as skeletal muscle development." (PMID 25063768, 2014).
brain tumor (3 papers, 2005 to 2020). "The regulation of DLK1 expression is poorly understood, but some elements of the brain tumor microenvironment such as hypoxia have been shown to drive DLK1 expression." (PMID 33142235, 2020). "This is true for Notch receptors and canonical Notch ligands such as Dll1 and Jag1 —some of the closest relatives to DLK1—and for proteins involved in brain tumor and neural stem cell maintenance like CD44 and p75NTR." (PMID 32205867, 2020). "Together, our findings suggest that soluble DLK1 is a niche-derived mediator of aggressive tumor growth in brain tumors." (PMID 33142235, 2020).
endometrial cancer (3 papers, 2021 to 2025). Primary or metastatic malignant neoplasm involving the endometrium (mucous membrane that lines the endometrial cavity). "In addition, CDKN1C and DLK1 appear to be hormonally regulated, with the former decreasing after expose to estradiol in endometrial cancer cells, while the latter decreasing after treatment with estradiol in girls with anorexia nervosa or human uterine leiomyoma cells." (PMID 37700362, 2023).
hypothyroidism (3 papers, 2018 to 2022). Abnormally low levels of thyroid hormone. "In an animal model a regulatory mutation causing partial loss of imprinting of the Dlk1-Dio3 cluster caused embryonic hypothyroidism in the offspring." (PMID 30279699, 2018). "The animals exhibit postnatal hypothyroidism and impaired brown tissue development due to overexpression of Dlk1, leading to lifelong hypothyroidism, obesity and glucose intolerance." (PMID 30279699, 2018). "For instance, a loss of Grf1 or Dlk1 resulted in reduced GH content and secretion, while disruption of the imprinting domain encompassing Dlk1, Rtl1, and Dio3 resulted in transient perturbation in the GH/IGF-1 growth pathway with hypothyroidism." (PMID 35025875, 2022). "Interestingly, an increased expression of DLK1 and DIO3 was observed in a large intrathoracic tumor of a patient who developed consumptive hypothyroidism." (PMID 33435319, 2021).
Infertility (3 papers, 2022 to 2024). "Finally, DLK1 encodes a growth regulator involved in infertility and genetic central precocious puberty in males that has been proposed as a link between metabolism and fertility; interestingly, DLK1 was found to be overexpressed in testicular tissue from SCO infertile patients." (PMID 39678461, 2024).
Kagami-Ogata syndrome (3 papers, 2020 to 2024). "In Kagami-Ogata Syndrome (KOS14), conversely, the loss of MEG3 expression would correlate with increased DLK1 and RTL1 expression, now from both the parental chromosomes." (PMID 38613389, 2024). "We also demonstrated that the severity of Kagami-Ogata syndrome exhibits good correlation with the degree of RTL1 overexpression but does not have any apparent correlation with the expression levels of DLK1, MIRG or other miRNA clusters." (PMID 32878913, 2020).
leukemia (3 papers, 2012 to 2025). A malignant (clonal) hematologic disorder, involving hematopoietic stem cells and characterized by the presence of primitive or atypical myeloid or lymphoid cells in the bone marrow and the blood. "A suggested annotation link between DLK1, cardiac phenotypes and leukemia could suggest another mechanism for a potential cross-disease role via NOTCH pathway modulation." (PMID 40832351, 2025). "Accumulating evidence suggests the opposing roles of these genes on growth and development are mirrored in leukemias, where DLK1 maintains cell stemness and enhances the proliferation of leukemic cells and MEG3 suppresses leukemogenesis and leukemic cell proliferation." (PMID 30876483, 2019). "High levels of DLK1 mRNA could be detected in BMMNCs of several MDS and leukemia patients." (PMID 23691477, 2012).
medullary thyroid carcinoma (3 papers, 2021 to 2026). "Our study reveals the characteristics of cancer stem cell subpopulations within medullary thyroid carcinoma (MTC) cell lines, highlighting the potential role of DLK1 in promoting the stemness phenotype." (PMID 39595993, 2024). "This study investigates DLK1 expression in two medullary thyroid carcinoma cells (MZ-CRC-1 and TT cells) and five non-medullary thyroid carcinoma cell lines (FTC133, BCPAP, XTC.UC1, KTC2, and 8505)." (PMID 39595993, 2024). "We next investigated DLK1 expression in medullary and non-medullary thyroid carcinoma cells, isolated subpopulations of MTC cells expressing DLK1 (DLK1+) and those lacking DLK1 expression (DLK1−) and subjected them to a detailed characterization of their expression of stem cell markers." (PMID 39595993, 2024).
metastatic tumors (3 papers, 2024 to 2025). "In 23 tumor samples from 17 mice (9 female), Dlk1 expression was low or absent in benign and pre‐malignant tumors, moderate in localized ACC, and higher in metastatic disease, both in the primary tumors and in lung metastases." (PMID 40035383, 2025).
Parkinson disease (3 papers, 2015 to 2023). A progressive degenerative disorder of the central nervous system characterized by loss of dopamine producing neurons in the substantia nigra and the presence of Lewy bodies in the substantia nigra and locus coeruleus. "In addition, dlk1 is involved in neuronal differentiation and Parkinson’s disease pathology along with other genes such as Nurr1 and Pitx3." (PMID 38051734, 2023). "We evaluated the recent literature on candidate blood biomarkers in Parkinson’s disease patients and observed five differentially methylated genes (COL9A2, SCNN1A, AMICA1, SLC16A3, and DLK1) in these studies within our conserved human regions." (PMID 32178731, 2020). "To further verify the role of nigral FA1/dlk1-ir cells we performed immunohistochemical analyses of FA1/dlk1 and TH in brain sections from 6-OHDA-lesioned rats (experimental model of Parkinson’s disease)." (PMID 25723595, 2015).
polycystic ovary syndrome (3 papers, 2019 to 2025). A disorder that manifests as multiple cysts on the ovaries. "DLK1 mutations were also associated with polycystic ovary syndrome (PCOS) and infertility, highlighting the connection between metabolism and reproduction." (PMID 39941454, 2025). "in a cohort of women with polycystic ovary syndrome (PCOS) with low DLK1 levels and an inverse correlation between HOMA-IR and DLK1." (PMID 36568069, 2022).
sarcoma (3 papers, 2013 to 2025). A usually aggressive malignant neoplasm of the soft tissue or bone. "We observed high DLK1 expression in a subset of these refractory cancers, such as sarcomas, SCLC, germ cell tumors, and grade 2 NE tumors." (PMID 40595495, 2025). "A factor in this could be that sarcoma gene changes are much more complex, than regenerating cells, thus binding of Dlk1 may not be sufficient to induce differentiation." (PMID 23577150, 2013).
type 1 diabetes (3 papers, 2014 to 2023). "Analysis of the paternally expressing delta-like 1 homologue (DLK1) shows that the paternal transmission of type 1 diabetes protective G allele of rs941576 single nucleotide polymorphism (SNP) results in significantly reduced birth weight (−132 g)." (PMID 25602077, 2015). "However, DLK1 is also associated with paternally inherited risk of type 1 diabetes, because the influence of SNP rs941576, which is in the imprinted region of chromosome 14q32.2 and at 105 kb downstream of DLK1." (PMID 37700362, 2023).
acute myocardial infarction (2 papers, 2017 to 2018). Necrosis of the myocardium, as a result of interruption of the blood supply to the area. "The Dlk1-Dio3 miRNAs miR-134 and miR-380 have been found to be enriched in plasma from patients with acute pulmonary embolism and acute myocardial infarction." (PMID 29996488, 2018). "In a mouse model of myocardial infarction, 29 miRNAs originating from the Dlk1-Dio3 cluster were activated in cardiomyocytes after induced tissue damage, suggesting their role in tissue remodeling efforts to replace damaged cardiac tissue." (PMID 28174625, 2017).
acute promyelocytic leukemia (2 papers, 2016 to 2021). An aggressive form of acute myeloid leukemia (AML), characterized by arrest of leukocyte differentiation at the promyelocyte stage, due to a specific chromosomal translocation t(15;17) in myeloid cells. "The overexpression of Dlk1-Dio3 miRNAs in acute promyelocytic leukemia (APL) has been associated with the hypermethylation of conserved binding sites for the CCCTC-binding factor (CTCF, an enhancer blocking protein) at MEG3-DMR." (PMID 34062726, 2021).
Anxiety (2 papers, 2019 to 2020). Intense feelings of nervousness, tension, or panic often arise in response to interpersonal stresses. "OX neurons are implicated in anxiety and depression, hence we explored whether loss of DLK1 expression from OXDLK1 neurons might contribute to these states." (PMID 33322758, 2020). "Developmental deletion or constitutive over-expression of DLK1 alters anxiety behavior and energy balance in adults and DLK1 has been implicated in suicide behavior." (PMID 33322758, 2020). "Given that DLK1 is only co-expressed by a subset of OX neurons, it will be important to determine if these neurons exert distinct, DLK1-amplified behavioral responses to anxiety compared to OX neurons that lack DLK1." (PMID 33322758, 2020). "Remarkably, dioestrus females show high anxiety in all these tests, and have significantly downregulated Dlk1 expression compared to proestrus females." (PMID 31253786, 2019). "It is also plausible that chromatin closing and downregulation of Dlk1 expression in ventral hippocampal neurons contribute to the high-anxiety phenotype observed during dioestrus." (PMID 31253786, 2019). "Taken together, these data and our current findings suggest that DLK1 might exert a pro-anxiety/depression/fear role, and that decreasing DLK1 expression could dampen these responses." (PMID 33322758, 2020). "In sum, these data suggest that LHA DLK1 plays an anxio-depressive role, and that decreasing DLK1 expression in the LHA can reduce anxiety and depression behavior." (PMID 33322758, 2020). "Adult-onset deletion of DLK1 reduced anxiety and depression behavior in mice, supporting a role for LHA DLK1 in behavior." (PMID 33322758, 2020). "Our finding that deleting DLK1 from adult OX neurons decreases anxiety behavior without altering energy balance suggests that DLK1 contributes to specific aspects of physiology and behavior." (PMID 33322758, 2020).
bladder cancer (2 papers, 2014 to 2016). "We measured copy number changes at DLK1 and both DMRs in the chromosomal region 14q32.2 by qPCR in bladder cancer tissues and cell lines to assess whether gene deletions were responsible for the decreased expression of the two genes in urothelial carcinoma." (PMID 25741387, 2014).
cardiac hypertrophy (2 papers, 2018 to 2024). "Several miRNAs in the Dlk1-Dio3 locus have been implicated in cardiac hypertrophy, and their dysregulated expression has been described in various cardiac disease models associated with hypertrophy." (PMID 29996488, 2018). "Moreover, DLK1+ cells were nearly absent in the myocardium from patients suffering from acute MI (n = 7 patients), chronic MI (n = 6 patients) or cardiac hypertrophy (n = 8 patients)." (PMID 38328889, 2024).
cardiomyopathy (2 papers, 2017 to 2024). A disease of the heart muscle or myocardium proper. "This is in accordance with cardiomyopathy being milder in humans with 14q32 deletions (devoid of Dlk1) than in partial trisomy of 14q32 exhibiting high Dlk1 expression." (PMID 38328889, 2024). "Since cardiomyopathy is mild in humans with 14q32 deletions (Dlk1 absence), yet severe in partial trisomy of 14q32 with Dlk1 overexpression, we hence speculated whether abnormal high Dlk1 levels present either in the pericardium or the myocardium may impact the scarring process after MI." (PMID 38328889, 2024). "A small number of other genes were regulated inversely in different adult forms of cardiomyopathy (RCM/DCM or RCM/ICM datasets) relative to RCM, including intelectin 1 (ITLN1), delta-like 1 homolog (DLK1), reelin (RELN), and myosin light chain kinase family, member 4 (MYLK4)." (PMID 28098235, 2017).
chordoma (2 papers, 2017 to 2025). Chordomas are rare malignant tumors arising from embryonic remnants of the notochord in axial skeleton. "We noticed that several of the down-regulated lncRNAs were all targeting on DLK1, the most under expressed coding gene in chordoma." (PMID 29348851, 2017). "As DLK1 was found to be the most differentially expressed protein-coding gene in chordoma (down regulated with FC 2771.79), we analyzed the lncRNAs that correlate with DLK1 specifically." (PMID 29348851, 2017). "Our lncRNA-coding genes profile data showed that the most differentially expressed protein coding gene in chordoma was DLK1, and Cis-regulation analysis revealed that this gene was targeted by a bunch of lncRNAs, most of which were identified to be different transcripts of MEG3 and MEG8." (PMID 29348851, 2017). "Concomitant down-regulation of the DLK1 and MEGs imply that imprinted genes may contribute to the development of chordoma." (PMID 29348851, 2017). "The expression analysis identified significant downregulation of SPOCK3, NRK, MYH8, DLK1 and SLN, alongside upregulation of HLA-DQA1, GDA, CXCL11, CXCL9 and ADAMDEC1 in chordomas." (PMID 40386066, 2025). "Our lncRNA-coding gene profile revealed concomitant down-regulation of DLK1 and MEG3 in chordoma samples." (PMID 29348851, 2017).
colorectal cancer (2 papers, 2023). A primary or metastatic malignant neoplasm that affects the colon or rectum. "In this report, we target tumor-derived pericytes expressing DLK1 with a clinically-relevant alpha type-1 polarized DC vaccine (αDC1) in a syngeneic mouse model of colorectal cancer." (PMID 37849752, 2023).
congenital heart defects (2 papers, 2024 to 2025). "As an example of DDKG queries driving new biological hypotheses, Method 8 also ranks DLK1, a non-canonical NOTCH ligand not previously strongly associated with congenital heart defects, within the top 200 genes." (PMID 40832351, 2025).
depression (2 papers, 2019 to 2021). "DLK1 and NOTCH signaling changes as mediated by miRNAs may an important avenue for future stress and depression-related studies." (PMID 34583641, 2021).
fibrosis (2 papers, 2022 to 2024). the formation of excess fibrous connective tissue in an organ or tissue in a reparative or reactive process. "Our results suggest that pericardial Dlk1 embraces a, so far, unnoticed role in the heart augmenting cardiac fibrosis through EMT." (PMID 38328889, 2024). "Dlk1 mRNA abundance progressively increased, the lowest levels observed in rats with mild/moderate fibrosis, the highest in cirrhotic rats." (PMID 35050550, 2022). "Likewise, DLK1 is expressed at increased levels in airway fibrosis in chronic obstructive asthma, where it facilitates collagen accumulation through integrin α5β1 signalling." (PMID 38328889, 2024).